CTSLP3 (cathepsin L pseudogene 3)
Synonyms: CTSL1P3; CTSLL3
Gene: Transcribed unprocessed pseudogene on chromosome 10 (46,758,089 to 46,759,199, forward strand). Ensembl gene ENSG00000280913.
Diseases named in the same sentence as CTSLP3 in open-access papers:
CTSLP3 is named in the same sentence as 2 diseases in open-access papers, as found by Europe PMC text mining. Sharing a sentence is not in itself a finding about the gene and the disease.
CTSLP3 shares sentences with these, for which no sentence is quoted: cancer (1 paper); tumor (1).